PCSK9 (proprotein convertase subtilisin/kexin type 9)
Diseases named in the same sentence as PCSK9 in open-access papers (continued):
Sharing a sentence is not in itself a finding about the gene and the disease.
infarction (5 papers, 2022 to 2026). A localised pathological necrosis of tissue resulting from obstruction of the blood supply usually by a thrombus, an embolus, or vascular torsion. "infarction expansion, this study further explored the effect of PCSK9 on fibroblast‐induced myocardial fibrosis by sequencing analysis." (PMID 41573336, 2026). "On day 1 post-infarction, liver Pcsk9 expression increased threefold from baseline, and then gradually decreased within one week mirroring the plasma PCSK9 levels." (PMID 39906341, 2024). "In 2023, Chen Wu and colleagues reported for the first time that a PCSK9 inhibitor can ameliorate post-infarction ventricular remodeling." (PMID 38383373, 2024). "On the basis of our results, we investigated the function of PCSK9 on cardiac macrophage polarization in mice after infarction." (PMID 35832650, 2022). "Our study is the first report to explain the possible mechanisms by which PCSK9 inhibition modulates the immunoregulatory functions of macrophages to promote heart repair after infarction." (PMID 35832650, 2022). "Inhibition of PCSK9 expression may induce switching of the macrophage phenotype from M1 to M2 and promote myocardial repair after infarction." (PMID 35832650, 2022).
malaria (5 papers, 2007 to 2022). Malaria is a serious and sometimes fatal disease caused by a parasite that commonly infects a certain type of mosquito which feeds on humans. "To date, there is no scientific evidence confirming the association between the therapy with PCSK9 inhibitors and the course of malaria." (PMID 35323699, 2022). "We have observed a significant association of the minor allele of the rs562556 PCSK9 SNP with reduced mortality in severe malaria." (PMID 33029265, 2020). "We previously reported an association of the GOF PCSK9 SNP rs505151 (c.2009 A > G, p.E670 G) with severe malaria in Malian children." (PMID 33029265, 2020). "Before exploring the association of the rs562556 PCSK9 SNP with malaria mortality, we determined the clinical predictors of fatal malaria in this Malian cohort." (PMID 33029265, 2020). "The role of PCSK9 mutation (a human cholesterol regulation mutation) has been described in malaria susceptibility." (PMID 29261755, 2017). "In this study, we investigated whether carrying the loss-of-function (LOF) rs562556 (c.1420 A > G; p.I474 V) PCSK9 single nucleotide polymorphism (SNP) affected the outcome of severe malaria in children." (PMID 33029265, 2020). "Association analysis of PCSK9 SNPs and uncomplicated malaria." (PMID 29447211, 2018). "Carriers of the minor allele of the E670G PCSK9 polymorphism might be more susceptible to severe malaria." (PMID 29447211, 2018). "As a first step, we have determined the frequency of four common PCSK9 SNPs with a documented cholesterolemia phenotype in sub-Saharan African children of Mali enrolled in a case-control study evaluating risk and protective factors for severe malaria." (PMID 29447211, 2018). "Data presented in this preliminary report support the notion that PCSK9 activity could affect susceptibility to malaria." (PMID 29447211, 2018). "A premature stop codon mutation in human PCSK9 (C679X) is considered to be under positive selection, and it is speculated that loss of PCSK9 function interferes with the life cycle of the malaria parasite through cholesterol restriction." (PMID 17971861, 2007). "Such a corroboration will justify the use of dietary or medicinal anti-PCSK9 interventions to attenuate the clinical course of malaria and reduce its mortality." (PMID 33029265, 2020). "Further investigation of the cholesterol regulating function of PCSK9 in the pathophysiology of malaria is needed." (PMID 29447211, 2018). "According to their results, a hypothesis that PCSK9 inhibitors could be useful for the therapy and prevention of malaria was formed." (PMID 35323699, 2022). "We therefore propose that expression of the relatively inactive PCSK9 variant specified by the G allele of the rs562556 SNP reduces the TG/HDL index which attenuates Plasmodium-caused systemic inflammation and improves prognosis in severe malaria." (PMID 33029265, 2020). "Since we presumed that plasma cholesterol level could influence the vulnerability to malaria, we examined the frequency of these cholesterolemia-modifying PCSK9 SNPs among healthy and malaria-stricken children in our cohort." (PMID 29447211, 2018). "We wanted to assess whether by affecting cholesterol metabolism, PCSK9 could influence the pathophysiology of malaria." (PMID 29447211, 2018). "We examined whether mortality to severe malaria occurred differentially between patients who carried the LOF G allele of the rs562556 PCSK9 SNP (AG and GG genotypes) and those who did not (AA genotype)." (PMID 33029265, 2020). "Furthermore, induction of normocholesterolemia with anti-PCSK9 drugs in hypercholesterolemic individuals could be useful for anti-malaria prophylaxis and therapy." (PMID 29447211, 2018).
muscle disorders (5 papers, 2024 to 2025). "Furthermore, it has been observed that muscle disorders induced by PCSK9 inhibitors are evident later in the treatment, with respect to statins." (PMID 38543150, 2024). "PCSK9 inhibitors appear to be effective and safe in this context and may be an appropriate option for patients with muscle disorders or statin contraindications." (PMID 39834954, 2024). "Unfortunateley, this hypothesis does not seem valid for muscle disorders induced by PCSK9 inhibitors or ezetimibe, since they do not deplete ubiquinone." (PMID 38543150, 2024).
nasopharyngitis (5 papers, 2017 to 2026). An inflammatory process that affects the nasopharynx. "Additionally, PCSK9 inhibitors were associated with an increased risk of influenza like illness and infections, such as nasopharyngitis and influenza." (PMID 36506552, 2022). "For instance, the most common treatment emergent adverse events seen in the PCSK9 inhibitor treated CKD patients from ODYSSEY clinical trials were nasopharyngitis, urinary tract infection, and upper respiratory infection." (PMID 41367297, 2025). "PCSK9 inhibitors (e.g., Evolocumab) enhance the LDL‐C receptors count in the liver by mediating degradation of the LDL‐C receptor, thereby lowering circulating LDL‐C levels, while PCSK9 inhibitors can lead to nasopharyngitis, upper respiratory tract infections, and other adverse reactions." (PMID 41523274, 2026). "Regarding the safety of PCSK9 inhibitors, no significant risk of AEs, SAEs, or nasopharyngitis were noted." (PMID 35444537, 2022). "In eight phase 2 and phase 3 trials that were eligible for the pooled analysis (1,879 FH patients), the clinical adverse events with PCSK9 antibody treatment mainly concerned headache, injection-site reactions, nasopharyngitis, gastroenteritis, nausea, and upper respiratory tract infections." (PMID 27458166, 2017). "In addition, for other adverse events, the rates of nasopharyngitis, headache, gastroenteritis, upper respiratory tract infections and injection-site reactions were greater but not significantly with than without PCSK9 antibodies." (PMID 27458166, 2017).
pulmonary fibrosis (5 papers, 2019 to 2025). Chronic progressive interstitial lung disorder characterized by the replacement of the lung tissue by connective tissue, leading to progressive dyspnea, respiratory failure, or right heart failure. "In our study, PCSK9 inhibition conspicuously improved cardiopulmonary function, RV remodeling, and lung fibrosis progression in PH mice model induced with BLM." (PMID 39722825, 2024). "The mechanisms of PCSK9’s impact on lung fibrosis were examined both in vivo and in vitro." (PMID 39722825, 2024). "Targeting PCSK9 expression or activity could effectively control lung fibrosis and its PH complication." (PMID 39722825, 2024). "Furthermore, The PCSK9 inhibitor exerts a protective effect against BLM-induced mouse lung fibrosis and MLE-12 cell injury through modulation of Wnt/β-catenin signaling and ultimately alleviating the development of PF-induced PH." (PMID 39722825, 2024). "PCSK9 inhibition or statin administration decreased NLRP3 production of respiratory epithelium and improved lung fibrosis in TGF-β1 overexpressing transgenic mice." (PMID 38762465, 2024). "PCSK9 transcripts are highly expressed in healthy individuals compared to COPD, pulmonary fibrosis or pulmonary systemic sclerosis." (PMID 39138259, 2024).
thyroid cancer (5 papers, 2014 to 2025). "Recent studies also indicate elevated PCSK9 levels in many types of cancers, including gastric, colorectal, hepatocellular, breast, and thyroid cancers, and the potential role of PCSK9 in cancer biology." (PMID 36986246, 2023). "Our objective was to determine if PCSK9 levels would rise in patients previously treated for thyroid cancer undergoing acute rhTSH stimulation." (PMID 24808925, 2014). "We tested whether an acute increase of TSH levels following administration of TSH in vivo would raise PCSK9 levels in patients who had previously undergone total thyroidectomy and radioablation for thyroid cancer." (PMID 24808925, 2014). "PCSK9 expression was significantly upregulated in ATC tissues compared to PTC, poorly differentiated thyroid cancer (PDTC), and normal thyroid tissues." (PMID 40328788, 2025).
acute respiratory distress syndrome (4 papers, 2021 to 2024). Progressive and life-threatening pulmonary distress in the absence of an underlying pulmonary condition, usually following major trauma or surgery. "Additionally, PCSK9 inhibition may protect against acute respiratory distress syndrome (ARDS) through its effects on lung injury and inflammation." (PMID 38333263, 2024).
bacteremia (4 papers, 2019 to 2022). "Plasma levels of inflammatory cytokines, TNF-α, IL-6, and IL-8 were decreased in septic patients with a PCSK9 loss of function allele while patients with bacteremia had increased PCSK9 plasma levels in a direct association with CRP." (PMID 34336112, 2021). "Furthermore, impaired elevation of plasma PCSK9 levels in patients with bacteremia was even associated with the need for more interventions and mortality." (PMID 35162992, 2022). "Therefore, it cannot be excluded that reduced circulating PCSK9 levels may have a favourable impact on bacterial sepsis outcomes, independent from pathogen lipid clearance." (PMID 31332258, 2019).
bladder cancer (4 papers, 2023 to 2025). "An analysis of the TCGA bladder cancer dataset recognized PCSK9 as a potential biomarker, with a strong correlation to OS of bladder carcinoma patients." (PMID 38185721, 2024). "No causal relationship was found between the lipid-lowering effect of lipid-regulatory medications (fibrates, probucol, statins, ezetimibe, proprotein convertase subtilisin/kexin type 9 [PCSK9] inhibitors, and evinacumab) and the risk of bladder cancer." (PMID 38188874, 2023).
cervical carcinoma (4 papers, 2016 to 2024). A carcinoma arising from either the exocervical squamous epithelium or the endocervical glandular epithelium. "Western blot analysis of OC cell line lysates identified variable expression of PCSK9 isoforms (uncleaved and cleaved) in comparison with cervical carcinoma HeLa cell line, which was previously shown to express PCSK9." (PMID 34359627, 2021).
coronary artery calcification (4 papers, 2018 to 2026). Calcification of the coronary artery, used as a measure of coronary atherosclerosis, a risk factor for myocardial infarction. "To date, there is a gap of evidence regarding the impact of PCSK9 inhibition on coronary artery calcification." (PMID 35600486, 2022).
End Stage Liver Disease (4 papers, 2017 to 2022). Final stage of a liver disease when the liver failure is irreversible and LIVER TRANSPLANTATION is needed. "In the present study, low PCSK9 serum concentrations were associated with higher mortality in patients with end-stage liver disease." (PMID 28727814, 2017). "Low PCSK9 serum concentrations were associated with higher mortality in patients with end-stage liver disease." (PMID 28727814, 2017). "The study aims to assess the associations between PCSK9, hypocholesterinemia, liver synthesis, cholestasis, MELD score and mortality in patients with end-stage liver disease." (PMID 28727814, 2017). "In a patient cohort with end-stage liver disease and mixed disease etiology, a negative correlation of serum PCSK9 concentrations with the MELD score was observed and low PCSK9 levels were associated with a higher mortality." (PMID 35162992, 2022). "A negative correlation was also found between PCSK9 levels and liver impairment, assessed by Model for End-Stage Liver Disease (MELD)." (PMID 32998342, 2020). "However, the present study was designed to investigate the alteration in lipid metabolism in patients with end-stage liver disease and not to prove the predicting value of PCSK9 levels for mortality in addition to the MELD score." (PMID 28727814, 2017).
endotoxemia (4 papers, 2017 to 2024). "In view of these findings, we hypothesized that the effect of a high fat load on intestinal permeability and endotoxemia could be associated with circulating PCSK9 levels in obese individuals." (PMID 32403394, 2020). "Thus, the aim of this study was to analyze the effect of a fat load on intestinal permeability, endotoxemia, and PCSK9 levels, as well as their possible association, in a population of obese individuals." (PMID 32403394, 2020). "Our results show that PCSK9 levels decrease after a fat load while zonulin and endotoxemia increase in individuals with morbid obesity." (PMID 32403394, 2020). "In conclusion, PCSK9 levels decrease while intestinal permeability and endotoxemia increase after a fat load in individuals with morbid obesity." (PMID 32403394, 2020). "This study aimed to analyze the relationship between PCSK9, intestinal permeability, and endotoxemia after a high fat load in obese individuals." (PMID 32403394, 2020). "Here we show that in a mouse model of endotoxemia induced by LPS administration, preventive or curative therapeutic approaches using a monoclonal antibody directed against PCSK9 at doses more than 10× higher than those used in humans did not reduce LPS-induced death." (PMID 28600283, 2017). "Here, we tested whether anti-PCSK9 antibodies prevent death from lipopolysaccharide (LPS)-induced endotoxemia." (PMID 28600283, 2017). "In both scenarios, the administration of PCSK9 antibodies did not alter endotoxemia-induced mortality." (PMID 28600283, 2017). "To test whether anti-PCSK9 antibodies as a monotherapy have a direct impact on endotoxemia and to rule out any potential synergic effect of treatment combinations, we did not use antibiotics." (PMID 28600283, 2017).
gallstones (4 papers, 2024 to 2025). Solid crystalline precipitates in the biliary tract, usually formed in the gallbladder, resulting in the condition of cholelithiasis. "As the levels of PCSK9 increase in the liver of individuals with gallstones, there is a corresponding increase in cholesterol levels, exhibiting a negative correlation with bile acid levels." (PMID 38509591, 2024). "Patients with cholesterol gallstones exhibited higher PCSK9 expression in their livers compared to those without gallstones." (PMID 41233786, 2025).
hypercoagulability (4 papers, 2021 to 2025). "In order to further support the association of PCSK9 wIthink hypercoagulable state, we analyzed the relation of PCSK9 with PT-t and found a similar result." (PMID 34809656, 2021). "Importantly, evolocumab treatment significantly reduced NETs accumulation, reinforcing the concept that PCSK9 inhibition blocked the platelet-neutrophil axis and suppressed thrombophilia." (PMID 41462858, 2025).
kidney damage (4 papers, 2023 to 2025). "In this study, we employed MR to explore the causal relationships between cholesterol-lowering drug targets (HMGCR, PCSK9, and NPC1L1) and the risk of developing diabetic microvascular complications (including nephropathy, retinopathy, and neuropathy)." (PMID 40225015, 2025). "This study evaluated the associations between genetic proxies of cholesterol-lowering drug targets (HMGCR, PCSK9, and NPC1L1) and the risk of diabetic complications, including nephropathy, retinopathy, and neuropathy." (PMID 40225015, 2025). "In contrast, PCSK9 inhibition was associated with a moderate increase in risk for nephropathy and neuropathy, but not retinopathy." (PMID 40225015, 2025). "In high-fat diet-fed mice, reduced circulating PCSK9 levels were found to promote CD36-dependent lipid accumulation in the kidneys, suggesting that PCSK9 may protect against lipid-induced kidney damage." (PMID 39765868, 2024). "Indeed, in our population PCSK9 levels were raised in women, in those with nephropathy and under statin treatment." (PMID 37620933, 2023).
liver dysfunction (4 papers, 2020 to 2025). "Moreover, a recent study found that hepatic reentry of plasma PCSK9 triggered the sensing loop regulating PCSK9 and low-density lipoprotein secretion, suggesting that liver dysfunction could change the circulating PCSK9 concentration and influence its function." (PMID 34996457, 2022). "Since PCSK9 inhibitors are not dependent on the hepatic CYP450 enzyme for metabolism, they may offer therapeutic advantages in patients with liver dysfunction or elevated baseline of ALT." (PMID 41235335, 2025).
lymph node metastasis (4 papers, 2020 to 2025). "Validation using the TCGA database further confirmed the correlation between high PCSK9 expression and TC invasion and lymph node metastasis, consistent with the expression patterns observed in patients from FUSCC." (PMID 40328788, 2025). "The high expression of PCSK9 in GC was significantly correlated with lymph node metastasis (P < 0.05)." (PMID 33489919, 2020). "Our findings demonstrated that high PCSK9 expression was correlated with lymph node metastasis and that it is the independent predictor for GC patients with poor survival." (PMID 33489919, 2020).
metastatic tumors (4 papers, 2022 to 2025). "Meanwhile, the expression level of PCSK9 in lung metastatic tumors was significantly suppressed in the PF846 treatment group." (PMID 40328788, 2025). "We also analyzed primary tumors and lung metastatic tumors derived from PCSK9‐overexpressing 231‐GFP cells that were implanted in the mammary fat pads of NOD/SCID mice." (PMID 40192514, 2025). "We verified the higher expression levels of PCSK9 and HMGCR in HB tumor samples as well as in metastatic tumors (diaphragm) by immunohistochemistry." (PMID 36612001, 2022). "Two million 231‐GFP cells overexpressing PCSK9 or an empty vector were injected into the mammary fat pads of NOD/SCID mice and within the 6 weeks period, we examined the development of orthotopic and metastatic tumors." (PMID 40192514, 2025).
Multiple Organ Failure (4 papers, 2019 to 2023). A progressive condition usually characterized by combined failure of several organs such as the lungs, liver, kidney, along with some clotting mechanisms, usually postinjury or postoperative. "A previous study has found that the risk of multiple organ failure increases significantly in patients with PCSK9 levels > 370 ng/ml." (PMID 37904138, 2023). "PCSK9 serum levels were highly correlated with the development of subsequent multiple organ failure which is a major mediator of mortality in ARDS." (PMID 35770004, 2022).